MTOR (mechanistic target of rapamycin kinase)
Diseases named in the same sentence as MTOR in open-access papers (continued):
Sharing a sentence is not in itself a finding about the gene and the disease.
autism (continued). "Our findings demonstrate that disruptions in mTOR and its signaling cascade components are widespread in the autism population and not limited to genetic forms of autism." (PMID 25627160, 2015). "Because of the well-established relation between autism and mTOR, we evaluated the brain mTOR levels in our autism rat model." (PMID 26218250, 2015). "Akt/mTOR pathway protein expression levels were examined in the fusiform gyrus of subjects with idiopathic autism versus control subjects." (PMID 25627160, 2015). "Several studies point to the Akt/mTOR pathway, which regulates translation at dendritic spines, as a potential molecular substrate of autism." (PMID 25627160, 2015). "Components of the mTOR pathway were assayed by Western blotting in postmortem fusiform gyrus samples from 11 subjects with idiopathic autism and 13 controls and in valproic acid versus saline-exposed rat neocortex." (PMID 25627160, 2015). "As a whole, these findings suggest that mTOR over-activation contributes to behavioral phenotypes of TSC-related autism and mTOR inhibitors offer potential therapeutic avenues for the pharmacological treatment of ASD-associated with mTORpathies." (PMID 25324723, 2014). "It is intriguing that yet another autism-associated gene, in this case EN2, implicates disordered Akt-mTOR-S6K signaling in the disease phenotype." (PMID 24507165, 2014). "Recently, Gkogkas and colleagues published exciting data on the role of downstream mTOR pathway in autism." (PMID 23533374, 2013). "Not only do they share features of impaired synaptic plasticity and dysregulation of mTOR, but they also share clinical features—autism, intellectual disability, cutaneous lesions, and tumors." (PMID 22619737, 2012). "A significant “hub” in the regulation of synaptic protein synthesis and neuronal survival is mTOR, and either excessive or insufficient signaling via this route is associated with autism, not necessarily causative." (PMID 40149774, 2025). "Interestingly, mTOR inhibitors have been shown to reverse autism-like behaviors in adult mouse models." (PMID 40149774, 2025). "mTOR plays a critical role in regulating synaptic morphology in autism." (PMID 41307793, 2025). "Notably, within the core network, MTOR (with a gene score of 2 and identified as a syndromic gene) and EIF4E (with a score of 3) are considered autism susceptibility genes." (PMID 39858558, 2024). "Thus, in both ‘low-mTOR’ ASD patients, we find that increasing mTOR pathway activity (via SC-79) can rescue ASD defects while reducing mTOR pathway activity (via MK-2206) in the Sibs reproduces autism NPC phenotypes." (PMID 38525876, 2024). "It has been suggested that the role of mTOR-mediated autophagy in the development of autism might be correlated with GABA." (PMID 37200987, 2023). "This suggests that disruption in the PI3K-Akt–mTOR pathway contributes to macrocephaly in autism." (PMID 37799731, 2023). "Recently, it has been additionally demonstrated that enhancing mTOR-mediated autophagy contributes to the restoration of GABAergic signaling, which might alleviate autism-like behaviors in rats." (PMID 37200987, 2023). "Our gene-set and gene network analyses revealed that on the whole, 222 out of 281 (79%) high-scored genes from the SFARI (Simon’s Foundation Autism Research Initiative) Gene database were connected with mTOR signaling activity and/or dependent on vitamin D3 availability directly or indirectly." (PMID 35055151, 2022). "Furthermore, a mouse study enriching the postnatal diet of 5-week-old mice with these three essential amino acids found decreased mTOR activity in the mouse brains and an effect on autism-related behaviors." (PMID 35631316, 2022). "Indeed, higher activity of mTOR, ERK, and p70S6 kinase and lower activity of GSK3 and tuberin (TSC2) were observed in children with non-syndromic autism, suggesting an increase in Akt/mTOR activity in idiopathic ASD." (PMID 35055151, 2022).
autism (continued). "Moreover, reduced Bdnf expression and excessive mTOR pathway activation have been reported, and Bdnf haploinsufficiency in human adolescents has been shown to be related to a higher score on an autism clinical rating scale." (PMID 35334932, 2022). "It is worth noting that, unlike immune dysregulation, microglial activation, and mitochondrial dysfunctions associated with autism, microbiota dysbiosis is not a consequence but, perhaps, the cause of mTOR signaling pathway activation." (PMID 35055151, 2022). "Together with the mTOR pathway, it can also regulate the severity of autism." (PMID 35178102, 2022). "Approximately 8-10% of autism cases have been identified due to an abnormal mTOR signaling pathway." (PMID 35422816, 2022). "In addition, here we discuss epidemiological studies linking the incidence of autism to birth seasons, clock gene polymorphisms in ASD and the role of the mTOR pathway as a common regulator of circadian rhythms and ASD pathogenesis." (PMID 33776640, 2021). "Nevertheless, abnormalities in the mTOR-dependent signalling pathway have been suggested in the pathology of several disorders, from neurodevelopmental syndromes in which autism is highly prevalent, to neurodegenerative disorders such as Alzheimer’s disease (AD) and Parkinson’s disease (PD)." (PMID 34576223, 2021). "The identified molecular mechanisms that link circadian dysfunction to autism (mTOR, MAPK, autism risk genes, etc.)could transform our understanding of ASD pathogenesis and provide new hope for ASD patients." (PMID 34943821, 2021). "Interestingly, the mTOR pathway is frequently dysregulated in developmental brain malformations, including autism, and is pharmacologically targeted to treat certain types of autism." (PMID 34943821, 2021). "Second, mTOR activation level finely controls dendritic spine pruning and shaping of synaptic connections at later stages of brain maturation but contrasting effects of mTOR overactivation upon spine density and morphology have been reported in autism models." (PMID 32329240, 2020). "Dysregulation of the mTOR pathway is hypothesized to be a common abnormality in autism, and mouse models with upregulated p-S6 have been shown to have autistic-like behaviors, including social behavior abnormalities." (PMID 31130852, 2019). "The percentages of exceptionally sensitive to mTOR activity mRNAs among the autism predisposition genes have never been evaluated before." (PMID 31847491, 2019). "Loss of function in multiple genes that negatively regulate mTOR, including TSC1, TSC2, PTEN, NF1, and FMR1, has been linked to syndromic autism with increased head size and high rates of seizures; both of these traits are also found in mice heterozygous for AMBRA1 loss of function." (PMID 31687209, 2019). "Therefore, other factors besides overactivation of mTOR must lead to excessive white matter in autism." (PMID 31024350, 2019). "Interestingly, ASD idiopathic cases and monogenic diseases related to autism have been linked to both higher and lower activity of the PI3K/AKT/MTOR axis." (PMID 31007884, 2019). "Notably, substantial papers have demonstrated that imbalanced mTOR signaling pathway and protein expression would give rise to various autism-like behaviors." (PMID 31849609, 2019). "Idiopathic autism and syndromic autism commonly involve increased mTOR activity." (PMID 31687209, 2019). "Here, we have demonstrated that the NL3 KO mice, as a monogenic model for ASD, had neuronal morphological abnormalities similar to these mouse models, which add to the evidence that the imbalanced PTEN/Akt/mTOR pathway leads to aberrant neuronal dendritic outgrowth in NL3-related autism model." (PMID 31849609, 2019). "Collectively, the studies of these monogenic mutated mouse models seemed to indicate a tight connection between autism and mTOR signaling pathway, naturally raising a question that whether NL3-related autism model is also associated with this pathway." (PMID 31849609, 2019).
autism (continued). "Given that schizophrenia has been characterized by reduced mTOR activation and increased synaptic pruning, it might be expected to show a different pattern from that of autism with regard to AMBRA1 expression, activity, and direction of effects." (PMID 31687209, 2019). "Interestingly, autism-relevant behavior in mouse models can be reversed by administration of mTOR inhibitors or mTOR pathway activators." (PMID 29691724, 2018). "It is supposed that mTOR signaling might be involved in the behavioral alleviation in autism-like behaviors in BTBR mice mediated by metformin treatment." (PMID 30555309, 2018). "Activation of mTOR is an effect that is also common to several of the genetic forms of autism." (PMID 29232822, 2017). "In fact, apart from TSC, developmental brain malformations, autism, and intellectual disability, there are also completely different conditions such as traumatic and hypoxic-ischaemic brain injury, and dementia that were already connected to mTOR dysfunction." (PMID 28386314, 2017). "Dysfunctions in the PI3K/mTOR pathway have gained a lot of attention in autism research." (PMID 26770665, 2016). "This raises a critical problem for understanding the neurobiology of autism and developing effective treatments: how do mutations in general regulators of growth, such as PTEN and other members of the PI3K-Akt-mTOR pathway, lead to the relatively selective behavioural and cognitive symptoms of ASD?" (PMID 27845329, 2016). "In the present study, we investigated whether the Akt/mTOR pathway, which is disrupted in monogenic disorders with high rates of autism, is altered in idiopathic autism." (PMID 25627160, 2015). "mTOR, a conserved serine/threonine kinase within cells, is a key molecule in controlling protein synthesis and cell growth, and also involved in neurological disorders including autisms and ADHD." (PMID 25647412, 2015). "Moreover, excessive signaling through the mTOR pathway has been considered a biomarker of autism, which corroborates our rat model of autism." (PMID 26218250, 2015). "Here, we investigated whether the Akt/mTOR pathway is disrupted in idiopathic autism and in rats exposed to valproic acid, an animal model exhibiting autistic-like behavior." (PMID 25627160, 2015). "The mTOR pathway is currently under investigation for the treatment of autism." (PMID 26218250, 2015). "Conversely, in our study, autistic subjects had significantly decreased p70S6K and eIF4B, while there were no changes in 4E-BP1 or eIF4E in these patients, pointing to specific deficits in mTOR-dependent translation via the p70S6K/S6 pathway in idiopathic autism." (PMID 25627160, 2015). "Additionally, autism-like phenotypes have been observed in Eif4ebp2 knockout and eIF4E-overexpressing mice, both downstream mTOR effectors regulating protein translation." (PMID 25627160, 2015). "Moreover, excessive signaling through the mTOR pathway has been considered a biomarker of autism, corroborating our rat model of autism." (PMID 26218250, 2015). "One candidate signaling pathway that may have a critical role in autism is the PI3K/AKT/mTOR pathway." (PMID 24795561, 2014). "There is a growing consensus that gene mutations associated with the regulation of the phosphoinositide 3-kinase/AKT/mammalian target of rapamycin (PI3K/AKT/mTOR) intracellular signaling pathway play a significant role in mediating the behavioral abnormalities that characterize autism." (PMID 24795561, 2014). "A number of mutations involving the regulatory molecule mTOR and its negative control molecule Pten have been linked to autism." (PMID 22747567, 2012). "However, the exact role of PI3K-AKT/mTOR signaling pathway in the autism remain to be clarify." (PMID 38145174, 2024).
autism (continued). "However, translational attempts of mTOR inhibition have been unsuccessful in ameliorating cognitive functioning, behavioral problems, autism and neuropsychological deficits in children ages 4-17 treated with Everolimus—another mTOR inhibitor that was previously FDA approved for cancer treatments." (PMID 36792602, 2023). "Taking into account the complexity of mTOR-regulated processes, even subtle alterations in the mTOR-dependent signalling cascade may lead to severe neurological defects typical for both neurodevelopmental, such as autism, and neurodegenerative disorders." (PMID 37108467, 2023). "Moreover, it was shown that inhibition of mTOR improves ASD-like behaviours related to Tsc2 or Tsc1 haploinsufficiency (in several Tsc1+/− or Tsc2+/− animal models), pointing to mTOR attenuation as an effective strategy in various mTOR-related brain dysfunctions, including autism." (PMID 37108467, 2023). "Thus, the circadian clock and autism are both regulated by mTOR signaling pathways." (PMID 33776640, 2021). "The autism-risk gene, phosphatase and tensin homolog on chromosome ten (PTEN), originally identified as a tumor suppressor gene, negatively regulates cell proliferation and growth by downregulating the phosphatidylinositol 3-kinase/AKT/mammalian target of rapamycin (PI3K/AKT/mTOR) pathway." (PMID 33504340, 2021). "Studies have shown that overexpressing the 4E-BP downstream activator EIF4E in mice leads to mTOR hyperactivation-like phenotypes such as neuroplastic abnormalities, synaptic dysfunction, repetitive behaviors, and sociability defects, all reminiscent of symptoms observed in individuals with autism." (PMID 34828352, 2021). "The hypothesis was supported by multiple studies demonstrating that pharmacological and natural mTOR-pathway inhibitors improve the behavioral problem, and in the case of vitamin D3 supplementation, even the core symptoms of autism in animal models or even in ASD-affected children." (PMID 31847491, 2019). "Products of mTOR that contribute to translation such as p70 ribosomal S6 kinase 1 (Sgk1) and eukaryotic translation initiation factor 4 E-binding proteins (4E-BPs) may play a role in autism." (PMID 31024350, 2019). "Indeed, a recent preclinical study of adult rats with TSC2 mutations and developmental status epilepticus, and a case study of a patient with TSC both reported improvements in social deficit behaviors, including autism-related behaviors, following mTOR inhibitor therapy with everolimus." (PMID 28288694, 2017). "mTOR inhibitors may also be a rational candidate for the management of neurodevelopmental/neuropsychiatric disabilities associated with TSC, including intellectual disability and autism." (PMID 28288694, 2017). "Lastly, autism has been associated with brain overgrowth, cortical malformations, and aberrant growth trajectories, further suggesting that dysfunctions in the PI3K/mTOR pathway, an important regulator of cell growth, might contribute to the autism etiology." (PMID 26770665, 2016). "Reduced TrkB might also contribute to the Akt/mTOR pathway down-regulation seen in idiopathic autism, since TrkB-FL contains the intracellular catalytic tyrosine kinase domain needed to activate TrkB-mediated signaling cascades, including the Akt/mTOR pathway, upon BDNF binding." (PMID 25627160, 2015). "The findings of our study however do not support the hypothesis and suggest that rare variants in the studied mTOR pathway candidate genes do not play a significant causal role in autism." (PMID 23514105, 2013). "AKT1, a core serine/threonine kinase within the PI3K/AKT pathway, is inhibited by CHR via the PI3K/AKT/mTOR axis, as evidenced by reduced AKT expression and ameliorated neuropathology in a propionic acid-induced rat autism model." (PMID 40808684, 2025). "Alterations in Akt/mTOR and MAPK/ERK signaling pathways are common pathological features of neurodevelopmental disorders, including non-syndromic, idiopathic forms of autism." (PMID 35137321, 2023).